INS (insulin)
Diseases named in the same sentence as INS in open-access papers (continued):
Sharing a sentence is not in itself a finding about the gene and the disease.
Obesity (continued). "Most studies have focused on the development of obesity and insulin insensitivity in rodent models of either genetic or diet-induced obesity after several weeks on a HF diet." (PMID 25170916, 2014). "Interestingly, a recent study has demonstrated that HFD potentiated Tau pathology in a mouse model of Tauopathy, in a manner independent from insulin resistance, suggesting that other factors, probably linked to obesity, might be implicated in Tau pathology during T2DM." (PMID 24574966, 2014). "This inflammation, in turn, can interfere with insulin signaling and results in the metabolic dysfunction found in obesity and type 2 diabetes." (PMID 25365383, 2014). "When compared with metformin users, obesity was substantially less prevalent in users of sulfonylurea (PR: 0.5, 95% CI: 0.4–0-8), and insulin and analogues (PR: 0.4, 95% CI: 0.3–0.7)." (PMID 25369331, 2014). "In later phase of obesity when insulin sensitivity is compromised, both NO- and EDHF-mimetic effects of leptin are impaired leading to unopposed stimulation of SNS and blood pressure elevation." (PMID 24475175, 2014). "These mice lacking IR in BAT-specific manner under STD showed severe brown lipoatrophy, susceptibility to the obesity (mainly in gonadal WAT compartment), glucose intolerance and a defect in insulin secretion." (PMID 25077985, 2014). "Decreased plasma adiponectin has been found in patients affected by obesity, type 2 diabetes and other insulin-resistant states, despite increasing amounts of fat tissue." (PMID 24972069, 2014). "In the subgroup of obese individuals with T2D, we found a dissociation of a cluster more closely related to lipid metabolism markers and a cluster containing obesity, insulin sensitivity, glucose homeostasis, and inflammation parameters." (PMID 24968098, 2014). "The aim of the study was to characterize the effect of a novel selective α-MSH analog on obesity and insulin sensitivity." (PMID 24204009, 2014). "Future long-term studies should be conducted to confirm that astaxanthin inhibits the early phase of obesity-related colon tumorigenesis by improving insulin resistance and the imbalance of adipokines in several animal models." (PMID 25515685, 2014). "In recent studies, a link between obesity, diabetes and breast cancer has been made through insulin/insulin-like growth factor and PI3K/Akt/mTOR signaling pathways and through obesity-induced chronic inflammation caused by adipose tissue dysfunction." (PMID 24978626, 2014). "In this context, we previously identified adiponectin, progranulin, chemerin, Fetuin-A and RBP4 serum concentrations as significant predictors of insulin sensitive or metabolically healthy obesity." (PMID 24968098, 2014). "These synthetic peptides regulate energy balance, but also normalize glycemia and insulin sensitivity in rodent models of obesity." (PMID 25352831, 2014). "Earlier research showed that EA was an effective treatment for obesity and can decrease serum glucose levels by increasing insulin secretion." (PMID 25024728, 2014). "Among adenoma-free controls, there were similar differences in measures of obesity, adiponectin and leptin, fasting glucose, insulin, and smoking status between African Americans and Caucasians." (PMID 25197277, 2014). "Adipose-specific RAPTOR knockout mice show similar properties with those long-lived mice, including increased leanness and resistance to diet-induced obesity accompanied by improved glucose tolerance and insulin sensitivity." (PMID 24474199, 2014). "The crude prevalence of obesity ranged from 19% (insulin and analogues users) to 49% (metformin users)." (PMID 25369331, 2014). "Increased energy expenditure can extend lifespan and alter insulin sensitivity and resistance to obesity." (PMID 25239873, 2014). "Upon HF feeding, we found Nrf2−/− mice exhibit partial protection against obesity, increased energy expenditure, and better glucose disposal and insulin sensitivity than HF-fed Nrf2+/+ mice." (PMID 24958099, 2014).
Obesity (continued). "Based on these unclear answers for the mechanism of the association between BMI and GA/A1c ratio, we tried to explain this mechanism with respect to BMI, a representative parameter for obesity, and insulin secretory function." (PMID 24586809, 2014). "Tregs are abundant in visceral adipose tissue of lean mice, but their number is significantly reduced in insulin-resistant mice models of obesity; similarly, a reduced number of Foxp3+ Treg cells was found in visceral adipose tissue from obese humans." (PMID 24823865, 2014). "For example, recent studies have revealed the link between inflammasomes, a group of protein complexes that recognize inflammation-inducing stimuli, and obesity, metabolic syndrome, insulin signaling and atherosclerosis." (PMID 25365383, 2014). "Of note, chronic infusion of the mammalian octopamine analogue noradrenalin into the ventromedial hypothalamic nucleus (VMH) of rats induces obesity, most likely due to hyperphagia and increased levels of circulating insulin and triglycerides." (PMID 25187989, 2014). "Insulin clearance is impaired in obesity and a defect in IDE activity is proposed as a major factor." (PMID 24740421, 2014). "Visfatin also known as pre-B cell colony enhancing factor (PBEF) or nicotinamide phosphoribosyltransferase (NAMPT) is a 52-kDa protein with apparently insulin-mimetic actions and increased plasma concentrations in patients with obesity and T2D." (PMID 24829560, 2014). "The findings from our in vitro and in vivo studies on the effects of SCO on adipocyte development and function and insulin action indicate its potential as a therapeutic capable of promoting metabolically advantageous changes in the context of obesity/T2DM." (PMID 24915004, 2014). "This was indicated by results of fasting serum glucose, I.V. glucose and insulin tolerance tests, lipid profile, and obesity index in both F2 and FG groups." (PMID 25045706, 2014). "This is because leptin biosynthesis increases under conditions of obesity, due in part to enhanced post- and pre-transcriptional effects of insulin and glucocorticoids." (PMID 25375630, 2014). "Plx is the Drosophila ortholog of the related human Rab GAPs TBC1D1 and TBC1D4/AS160 that regulate the insulin-controlled traffic of the glucose transporter GLUT4 and have been linked to obesity." (PMID 25453831, 2014). "Reduced CNS insulin signaling from either defective secretion or action, contributes to the pathogenesis of common metabolic disorders, including diabetes and obesity." (PMID 25722876, 2014). "Increased macrophage infiltration in tissues including white adipose tissue and skeletal muscle has been recognized as a pro-inflammatory factor that impairs insulin sensitivity in obesity." (PMID 24911652, 2014). "Unbiased, distance-based hierarchical cluster analyses were performed to recognize patterns among adipokines and their relationship with parameters of obesity, glucose metabolism, insulin sensitivity and inflammation." (PMID 24968098, 2014). "At the systemic level, obesity is associated with elevated pro-inflammatory cytokines TNF-a and IL-6, NEFA and basal concentrations of insulin." (PMID 24722524, 2014). "Obesity-related effects on insulin levels and the insulin-like growth factor-1 (IGF-1) axis, some adipokines, and inflammatory cytokines also stimulate breast cancer growth and metastasis, both directly and most probably by enhanced angiogenesis." (PMID 24693452, 2014). "Future studies are needed to determine if obesity plays a role in altering pancreatic α2‐adrenoceptor activation after hemorrhage, resulting in exaggerated suppression of both insulin and glucagon secretion." (PMID 25472607, 2014). "The approach of using EA to treat other insulin-resistant conditions such as obesity seems to be a good reference for understanding the effect of EA on glucose metabolism and insulin activity." (PMID 25024728, 2014).
Obesity (continued). "First, we determined the association of MAP3K8 (TPL2/COT) expression in human adipose tissue with measures of obesity (BMI), adipose tissue inflammation (cytokine expression) and insulin resistance (plasma insulin)." (PMID 24586913, 2014). "IL-17 has been found to be produced by T cells in adipose tissue, and IL-17 knockout mice are overweight and have increased obesity following high-fat diet compared to littermate controls, but show improved insulin sensitivity." (PMID 25157251, 2014). "Obesity and progression to insulin were found to predict the odds of being an HC patient and are two modifiable factors for T2DM patients." (PMID 24576356, 2014). "At its early stages, obesity results in resistance of peripheral tissues to insulin, through an increase in circulating triglycerides, and the release of adipokines, peptides with a multitude of endocrine and paracrine effects." (PMID 25268492, 2014). "The observation that activation of the adaptive UPR leads to enhanced insulin sensitivity with decreased obesity has been described previously." (PMID 24465394, 2014). "We first studied influence of probiotic administration for insulin sensitivity in rat model of MSG-induced obesity." (PMID 25030027, 2014). "DGAT1 null mice are known to be resistant to diet-induced obesity, and more insulin sensitive relative to the wild-type; however, the mice exhibit abnormalities in the skin." (PMID 25405858, 2014). "We have identified four salivary biomarkers in 10-year old subjects that change significantly with increasing obesity; insulin, CRP, adiponectin and leptin." (PMID 24915044, 2014). "Calorie restriction (CR), an effective anti-obesity strategy with potent anticancer effects, has been shown to reduce serum levels of insulin, leptin, and IGF-1 and decrease the expression of protumorigenic cytokines." (PMID 24804677, 2014). "Both regulatory and inflammatory T cells are found in VAT and influence the recruitment and function of other inflammatory cells into VAT, thereby contributing to changes in insulin sensitivity in obesity." (PMID 25157251, 2014). "C57BL/6 mice fed a high-fat diet (HFD, ∼35% lipids) for 8 weeks that become obese and insulin-resistant (diet-induced obesity, DIO) were used." (PMID 25013446, 2014). "Findings: Weight, body mass index, waist circumference, insulin, alanine transaminase, and high sensitive C-reactive protein values were markedly higher in obesity group when compared with controls (P<0.001)." (PMID 25755863, 2014). "Our experience in mouse obesity models is that treatment with agents that selectively target and improve, i.e., normalize, hepatic aPKC leads to restoration of normal insulin signaling and action in muscle, even while high fat feeding continues." (PMID 26237474, 2014). "By contrast, the secretion of adiponectin, an adipokine with anti-inflammatory, anti-obesity, insulin sensitizing, and vasorelaxing, that is, metabotrophic activity, is decreased in obesity and related vascular diseases." (PMID 24782857, 2014). "With endothelial dysfunction in obesity arising from altered insulin signaling or fatty acid-induced inflammation, these transport mechamisms are compromised." (PMID 24552349, 2014). "Increased adipose tissue RAAS activity by diet-induced obesity promotes inflammation, lipogenesis and reactive oxygen species generation, and impairs insulin signaling, all of which worsen the adipose environment." (PMID 25280587, 2014). "Hyperinsulinemia in Mat-Ob offspring before the onset of obesity indicate that they were insulin-resistant at this age." (PMID 24789994, 2014). "The strongest predictor of being an HC patient was having a CCI score of 2 or greater (odds ratio [OR] = 4.896), followed by a diagnosis of obesity (OR = 2.106), renal impairment (OR = 2.368), and insulin use (OR = 2.098)." (PMID 24576356, 2014).
Obesity (continued). "In contrast, modest increases in leucine intake, sufficient to induce plasma leucine elevations to ~0.5 mM, significantly reduced obesity-related oxidative and inflammatory stress, resulting in improvement of insulin sensitivity in humans." (PMID 25400942, 2014). "DGAT1 null mice are resistant to diet-induced obesity, and exhibit higher insulin sensitivity compared to the wild-type." (PMID 25405858, 2014). "Obesity and aging are characterized by decreased insulin sensitivity (IS) and muscle protein synthesis." (PMID 25139155, 2014). "SCD−/− mice fed a high fat diet display protection against diet-induced obesity and increased insulin sensitivity due to an upregulation of fatty acid oxidation and downregulation of lipogenesis." (PMID 25500563, 2014). "The current study demonstrates that maternal diet-induced obesity leads to impaired adipose tissue insulin signalling in young mice of obese mothers through reduced IRβ, IRS-1 and the p110β catalytic and p85α regulatory subunits of PI3K." (PMID 24749062, 2014). "Reports on the levels of circulating resistin found in individuals with obesity and T2DM is controversial, but it is clear that resistin is associated with reduced insulin sensitivity." (PMID 25386661, 2014). "It is well accepted that adipocyte hyperplasia in obesity can lead to an increased fat cell number with smaller more insulin sensitive adipocytes." (PMID 25163748, 2014). "In the adipose tissue, it functions as an adipokine by activating the Jak2/Stat5 pathway that inhibits insulin signaling and promotes obesity." (PMID 24695525, 2014). "It has been demonstrated that IL-37 has the properties of reducing obesity-induced adipose tissue inflammation and improve insulin sensitivity." (PMID 25226272, 2014). "Together, these findings reveal effects of DHA and its bioactive SPMs in preventing obesity-induced insulin resistance via mimicking insulin sensitizing and expression of adiponectin." (PMID 25528960, 2014). "Dietary administration of fenofibrate effectively inhibited obesity-related lung tumorigenesis by inhibiting the insulin–IGF axis and improving hyperinsulinemia." (PMID 24857924, 2014). "Despite its unclear role in insulin sensitivity, BCAAs also seem to play a role in the development of coronary disease, which is another possible consequence of obesity." (PMID 25257998, 2014). "Specifically, myocardial overexpression of MED13 (or inhibition of its regulatory microRNA, miR-208a) led to resistance to obesity and systemic insulin-resistance when challenged with high-fat feeding." (PMID 24932507, 2014). "Caffeic acid also exhibited antiobesity effects by reducing body and visceral fat-pad weights, plasma levels of lipids, and obesity-related hormones such as leptin and insulin in HFD-fed mice." (PMID 24624222, 2014). "Among the three groups of patients with PCOS differing by the obesity status, lipid profile and insulin action worsened and β-cell insulin release increased significantly with the increasing BMI." (PMID 24705280, 2014). "For example, macrophages recruited under conditions of obesity appear to be more inflammatory, which impair insulin signaling in tissues through inducing inflammation." (PMID 24911652, 2014). "Inversely expressed with obesity, the adipokine adiponectin has overall positive insulin-sensitizing and metabolic effects via signaling in various tissues such as liver and skeletal muscle." (PMID 24552349, 2014). "Body composition, glucose, insulin sensitivity, and lipids were assessed in diet-induced obesity (DIO) mice and Zucker Diabetic Fatty (ZDF) rats after oral administration." (PMID 24498211, 2014). "Treatment with the pan-HDACs inhibitors sodium butyrate or the class I HDAC inhibitor MS-275 improves insulin sensitivity in mice with diet-induced obesity and obese db/db mice, respectively." (PMID 25610877, 2014).
Obesity (continued). "In 2009, Nature Medicine published a series of three papers that altogether established a critical role for both inflammatory and regulatory T cells in mediating adipose tissue inflammation and altering insulin sensitivity in obesity." (PMID 25157251, 2014). "Resident tissue macrophages aid in tissue homeostasis, but obesity can promote low-grade inflammation in insulin sensitive tissues." (PMID 25216251, 2014). "Insulin signaling downstream of Akt and aPKC in liver is particularly important for understanding how metabolic abnormalities arise in obesity and T2DM." (PMID 26237474, 2014). "Patients were significantly more likely to be high-cost if they had comorbid conditions, a diagnosis of obesity, or used insulin." (PMID 24576356, 2014). "A dominant shift occurred from proinflammatory M1 to anti-inflammatory M2 macrophage phenotypes, which contributed to an improved impaired glucose tolerance and insulin sensitivity in response to diet-induced obesity in these animals." (PMID 24895488, 2014). "To this end we studied grizzly bears (Ursus arctos horribilis) before, during, and after hibernation to determine the effects of natural obesity on insulin sensitivity and cardiac function." (PMID 25553771, 2014). "Resveratrol is known to reduce fat accumulation and improve glucose tolerance and insulin sensitivity in mice with high-fat diet-induced obesity." (PMID 25114710, 2014). "In other clinical conditions that are included among the principal criteria for MS, such as obesity and arterial hypertension, a significant correlation between NOx and insulin levels was found." (PMID 24987495, 2014). "Chronic inflammation due to obesity-induced ectopic tissue, such as liver and muscle lipid accumulation further exacerbates insulin resistance." (PMID 25239110, 2014). "This is because obesity increases insulin release which then thickens blood vessels in addition to release of renin and aldosterone." (PMID 25135002, 2014). "Nnt encodes a mitochondrial protein that catalyses the production of NADPH and mice with the Nnt mutation develop asymptomatic metabolic syndrome characterized by glucose intolerance and obesity-independent reduced insulin secretion." (PMID 25066696, 2014). "Studies were included which clearly defined the MHO group (using either insulin sensitivity and/or components of metabolic syndrome AND obesity) and its association with either all cause mortality, CVD mortality, incident CVD, and/or subclinical CVD." (PMID 24400816, 2014). "The present findings corroborate previous studies that showed an impaired interaction between leptin and insulin and the mesolimbic reward circuitry in obesity." (PMID 25368558, 2014). "Diet-induced obesity leads to insulin insensitivity and numerous studies have shown that obesity and insulin insensitivity are related to the presence of low-grade inflammation." (PMID 25170916, 2014). "Our results differ from those in number of animal models which document effects of exposure to a maternal high-fat diet on offspring obesity and glucose-insulin homeostasis." (PMID 25082159, 2014). "Another aspect of linking the NADPH oxidases with overweight/obesity is the impact of free radicals on insulin resistance condition." (PMID 24477591, 2014). "Knockout studies of GPR61 in mice exhibit hyperphagia-induced obesity and higher plasma insulin levels." (PMID 25502755, 2014). "In our study, AT1R blockade administration promoted normalization of the metabolic and cardiovascular disturbances, including cardiac remodeling and insulin resistance, arising from hypercaloric diet-induced obesity." (PMID 24466104, 2014). "Obesity results in adipose-resident FoxP3+ Treg depletion and gain-of-function experiments to expand their numbers improved insulin sensitivity." (PMID 24710396, 2014).